BPIFA2 (BPI fold containing family A member 2)
Description:
Has strong antibacterial activity against P.aeruginosa.
Synonyms: PSP; C20orf70; SPLUNC2; bA49G10.1
Tractability: Antibody: its Gene Ontology location is reachable by antibodies, with high confidence; UniProt places it where antibodies can reach, with medium confidence; UniProt predicts a signal peptide or a membrane-spanning region.
Gene: Protein-coding gene on chromosome 20 (33,161,768 to 33,181,412, forward strand). Ensembl gene ENSG00000131050.
Subcellular location: Secreted
Pathways (Reactome):
Immune System: Antimicrobial peptides
Gene Ontology:
Molecular function: lipopolysaccharide binding; protein binding; lipid binding
Cellular component: extracellular exosome; extracellular region; secretory granule
Genetic constraint (gnomAD): Loss-of-function variants: 18 observed, 23.8 expected, observed/expected ratio (o/e) 0.76, 90% interval 0.52 to 1.12. The upper end of that interval is the gene's LOEUF score, 1.12, which puts it in group 4 of 6, group 1 being the genes least tolerant of losing a copy. Missense variants: 280 observed, 294.37 expected, observed/expected ratio (o/e) 0.95, 90% interval 0.86 to 1.05. Synonymous variants: 117 observed, 123.16 expected, observed/expected ratio (o/e) 0.95, 90% interval 0.82 to 1.11.
Homologues: Orthologues: chimpanzee BPIFA2 (99% identical), macaque BPIFA2 (86% identical), dog BPIFA2 (52% identical), pig BPIFA2 (50% identical), mouse Bpifa2 (31% identical), rat Bpifa2 (29% identical), Caenorhabditis elegans C06E8.5 (15% identical). Paralogues in human: BPIFA1 (23% identical), BPIFB1 (22% identical), BPIFB3 (18% identical), BPIFB4 (16% identical), BPIFB6 (15% identical), BPIFA3 (15% identical), BPIFC (15% identical), BPIFB2 (12% identical), CETP (12% identical), LBP (12% identical), PLTP (12% identical), BPI (10% identical).
Diseases named in the same sentence as BPIFA2 in open-access papers:
BPIFA2 is named in the same sentence as 19 diseases in open-access papers, as found by Europe PMC text mining. Sharing a sentence is not in itself a finding about the gene and the disease. The quoted sentences say what the papers report.
asthma (1 paper, 2022). "The activation of BPIFA2 after UPM exposure in asthma and COPD epithelium from the triple co-cultures in our study suggest the upregulation of innate immune response in the respiratory tract of patients with obstructive lung diseases after air pollution exposure." (PMID 36012391, 2022). "PCR analysis showed that mRNA expression of BPIFA2 and ENPEP was upregulated in both asthma and COPD, while the expression of CYP1B1-AS1 and TIPARP was increased in the epithelium from COPD patients only." (PMID 36012391, 2022). "We found that the mRNA expression of BPIFA2 and ENPEP was upregulated after UPM treatment, most potently in triple co-cultures of the asthma and COPD patients only." (PMID 36012391, 2022). "We showed that the most potently activated genes after air pollution exposure in the triple co-cultured epithelium of asthma and COPD patients were BPIFA2 and ENPEP, while CYP1B1-AS1 and TIPARP were upregulated in the COPD epithelium only." (PMID 36012391, 2022).
chronic kidney disease (1 paper, 2023). Impairment of the renal function secondary to chronic kidney damage persisting for three or more months. "In fact, besides its prominent role in the local antibacterial response, BPIFA2 exerted a role in the prevention of early fibrosis progression and the development of chronic kidney disease." (PMID 37569584, 2023).
lupus nephritis (1 paper, 2025). Glomerulonephritis in the context of systemic lupus erythematosus. "In lupus nephritis, LRP5 mediates renal injury by modulating mitochondrial function and increasing apoptosis in HK-2 cells, acting synergistically with BPI fold-containing family A member 2 (BPIFA2), which is a parotid secretory protein and a biomarker of renal injury." (PMID 40940800, 2025).
salivary gland tumors (1 paper, 2024). "Some of the identified peptides were derived from proteins previously suggested as potential biomarkers of salivary gland tumors (ANXA1, BPIFA2, FGB, GAPDH, HSPB1, IGHG1, VIM) or tumors of other tissues or organs (SERPINA1, APOA2, CSTB, GSTP1, S100A8, S100A9, TPI1)." (PMID 39201484, 2024).
viral infections (1 paper, 2021). "Genes involved in defense response to bacterial or viral infections such as BPIFA2, CD48, ULBP3, NKG2D ligand 1-like, and NKG2D ligand 4-like were reported to have more copies in the genomes of Nubian ibex relative to the domestic goat reference." (PMID 34142199, 2021). "BPIFA2 is a glycoprotein expressed in the airway epithelium and submucosal glands of the upper airways, where it offers protection against bacterial and viral infections." (PMID 34142199, 2021).
BPIFA2 also shares sentences with these, for which no sentence is quoted: sicca syndrome (3 papers); mucoepidermoid carcinoma (2); autoimmune disease (1); dry eye (1); enteropathy (1); head and neck cancer (1); lung adenocarcinoma (1); lung carcinoma (1); lung disease (1); obstructive lung diseases (1); papillary cystadenocarcinoma (1); systemic lupus erythematosus (1); T cell lymphoma (1); tumours (1).